TNF (tumor necrosis factor)
Diseases named in the same sentence as TNF in open-access papers (continued):
Sharing a sentence is not in itself a finding about the gene and the disease.
Obesity (continued). "It has been demonstrated that monocyte chemoattractant protein 1 (MCP-1) and tumor necrosis factor-α (TNFα) are important pro-inflammatory biomarkers involved in the development of obesity induced meta-inflammation." (PMID 32365527, 2020). "We then assessed the systematic inflammation through the detection of proinflammatory factor TNFα in the sera, which plays a key role in obesity-induced insulin resistance." (PMID 33208918, 2020). "It is considered that the transfer restores the Lin28/Let 7 pathway, involved in a feedback loop with nuclear factor-κB (NF-κB) and TNF-α, confirming that there is a link between obesity-induced inflammation and ASC cellular insulin resistance." (PMID 32452515, 2020). "During obesity there is an increase in the number of macrophages within the tissue, which are the source of TNF-α and other pro-inflammatory cytokines." (PMID 33353562, 2020). "The results propose Factor VII is an adipokine, enhanced by TNF-α or isoproterenol, which plays crucial role in the pathogenesis of obesity." (PMID 32027667, 2020). "The first major link made between inflammation and obesity identified the pro-inflammatory cytokine TNFα: tissues obtained from obese humans, as well as the adipose from murine models of obesity, had elevated TNFα expression." (PMID 32183037, 2020). "During obesity the phenotypic deviation of M2 to M1 macrophages in adipose tissue increases the production of proinflammatory cytokines such as TNF-α and IL-6, which inhibit the insulin receptor signaling." (PMID 32774333, 2020). "This study showed up-regulation of MiR-155 in biopsies of subjects with obesity where the induction of MiR-155 was correlated with tumor necrosis factor alpha (TNFA) expression and BMI." (PMID 33207733, 2020). "On the other hand, the reverse situation also appears to be true, since it was observed that insulin and obesity stimulates the gene expression of TNF-α and IL-6 in adipose tissue." (PMID 32187268, 2020). "In obesity, adipocytes grow, enlarge, and secrete inflammatory cytokines, such as tumor necrosis factor α, interleukin-6, and high-sensitivity C-reactive protein." (PMID 33092686, 2020). "Seminal studies of obesity have helped us to understand that macrophages secrete TNFα, which further enhances lipolysis, thereby driving metabolic dysfunction." (PMID 33488632, 2020). "It is known that adipose tissue in obesity secretes a high level of pro-inflammatory adipokines, such as leptin, TNFα and ILs, but few anti-inflammatory cytokines such as adipoQ." (PMID 31989870, 2020). "The serum levels of obesity-related metabolic signaling molecules, including insulin, adiponectin, lipopolysaccharide (LPS) and the cytokines interleukin (IL)-1β and tumor necrosis factor (TNF)-α, were markedly improved." (PMID 32244807, 2020). "Further research selectively targeting ATM genes confirmed their definitive role in obesity-associated metabolic disorders and inflammation by displaying an altered lipid and glucose metabolism as evidenced in lipoprotein lipase (LPL) and TNFα-depleted ATMs." (PMID 32752107, 2020). "The first evidence of link between inflammation, obesity and insulin resistance was the finding that increased expression of tumor necrosis factor α (TNFα), an inflammatory cytokine, promoted insulin resistance via serine phosphorylation of IRS1." (PMID 32524217, 2020). "Adipocytes are capable of secreting pro-inflammatory cytokines, including CCL2, TNF-α, and IL-6 and their production is significantly increased in obesity." (PMID 32318345, 2020). "As adipocytes are a known source of pro-inflammatory cytokines, including TNF-α, IL-1, and IL-6, obesity can be seen as a chronic inflammatory condition." (PMID 32691301, 2020). "A recent study has shown that a higher body mass index is associated with hypertriglyceridemia in PCOS patients, which is attributed to the obesity-induced change of adipokines, including tumor necrosis factor-alpha (TNFα), interleukin (IL)-6, and adiponectin." (PMID 32256193, 2020).
Obesity (continued). "TNFα is a cytokine found to be elevated in obesity and decreased when adiponectin is involved in lipogenesis." (PMID 32365527, 2020). "Obesity is a chronic low-grade inflammation, and the concentrations of resistin, leptin, and IL-1β, as well as TNF-α and IL-6, in peripheral blood of obese patients were significantly increased." (PMID 32104715, 2020). "In detail, it has been reported that obesity increases bone resorption by increasing the levels of TNFα and IL-6." (PMID 32635185, 2020). "Lastly, weight loss in obese subjects improved insulin sensitivity and reduced TNF expression in adipose tissue, suggesting a pivotal role of obesity on inflammation and insulin sensitivity." (PMID 33178196, 2020). "Our human adipose tissue data show high expression of MIP-1α/CCL3 and TNF-α in obese compared to lean individuals, and these markers are positively correlated in obesity state." (PMID 33050324, 2020). "The adipose tissue is the main source of circulating TNF-α in obesity, as its synthesis is increased by adipocytes in obese subjects and a weight-loss results in its low concentrations." (PMID 32650509, 2020). "Studies have also indicated that inflammatory cytokines such as IL-1β, TNF-α, and IL-6 which are increased in obesity and diabetes conditions modulate insulin signaling." (PMID 33293987, 2020). "Particularly, we confirmed that the extent of upregulation of three genes including IL-6, IL-1β, and TNF-α, i.e., the three most studied inflammatory genes related to obesity, was significantly greater in ‘Lean_Ag-DEGs’ than in ‘Obese_Ag-DEGs’ (P < 0.01)." (PMID 33183332, 2020). "While obesity alone increases pro-inflammatory IL-1β, TNFα, MCP1, and keratinocyte-derived chemokine, obesity decreased the extent to which TNBS-colitis increased IL-2 and IFN-γ in mesenteric adipose and intestinal tissues." (PMID 33603741, 2020). "TNF-α converting enzyme (TACE) drives macrophage homing by increasing the production of soluble TNF-α and is considered to be one of the major regulators of obesity-induced inflammation." (PMID 33298044, 2020). "An increased production of monocyte chemoattractant protein 1 (MCP1), interferon (IFN) α, IFNβ, TNFα, and IL-6 in adipose tissue has been reported in animal models of obesity." (PMID 33339214, 2020). "Meanwhile, TNF-α plays an important role in the process of inflammation, insulin resistance, diabetes and obesity." (PMID 32819324, 2020). "Obesity induced by fat-rich diets promotes increased levels of inflammatory cytokines such as TNF-α." (PMID 31553356, 2020). "Patients suffering from obesity in addition to periodontitis have a higher level of TNF-α expression than patients with periodontitis only." (PMID 32708317, 2020). "In fact, these M1 macrophages that are activated within the adipose tissue have been identified to be a major source of circulating TNFα and IL-6 during obesity, insulin resistance, and T2D." (PMID 32183037, 2020). "In this sense, TNF-α has received considerable attention as one of the key mediators of inflammation involved in obesity and is found in high concentrations in subjects with obesity than in lean." (PMID 32893859, 2020). "Obesity, especially central obesity, increases various pro-inflammatory molecules such as adipokines, interleukin-6, and tumor necrosis factor alpha, leading to the development of systemic insulin resistance." (PMID 32488147, 2020). "Additionally, randomized placebo-controlled, double-masked clinical trials of salsalate, IL1Ra, and anti-TNF-α are being adapted to investigate whether these anti-inflammatory approaches change disease risk in obesity, type 2 diabetes, and atherosclerotic cardiovascular disease." (PMID 32069832, 2020). "For that purpose, we focused on IL‐6, IL‐10, and TNF‐α, key pro‐ and anti‐inflammatory cytokines known to be dysregulated in obesity." (PMID 32614494, 2020).
Obesity (continued). "As obesity progresses, proinflammatory adipokines, including leptin, TNF, resistin, IL-6, RBP4, lipocalin-2, and ANGPTL-2, are preferentially synthesized and cause chronic inflammation." (PMID 33133214, 2020). "Studies have shown that mice fed a high fat diet and administered NanoSOD, showed improvement in obesity-related macrophage accumulation levels and inflammatory markers like TNFα, MCP1, and MMP12 improved." (PMID 32903449, 2020). "In adipose tissue, the secreted TNF-α is primarily derived from M1 macrophages and the accumulation of M1 macrophages during obesity contributes to the development of insulin resistance." (PMID 32686763, 2020). "In obesity, the dysfunctional adipose tissue (AT) releases increased levels of proinflammatory adipokines such as TNFα, IL-6, and IL-1β and free fatty acids (FFAs), characterizing a chronic, low-grade inflammation." (PMID 32947825, 2020). "In obesity, the adipocyte is dysfunctional with excessive production and secretion of pro-inflammatory adipokines, such as tumor necrosis factor α (TNF-α), interleukin 6 (IL-6), and leptin." (PMID 33597945, 2020). "On the other hand, obesity was associated with lower adiponectin and higher TNF-α concentrations, while HDL < 1.02 mmol/L was associated with higher TNF-α and lower adiponectin levels." (PMID 33202729, 2020). "The authors also showed that high-fat diet induced obesity resulted in systemic low-grade inflammation and increased proinflammatory cytokines expression in plasma (i.e., TNF-α, IFN-γ, IL-6, MCP-1β, IL-1, and IL-17)." (PMID 32887419, 2020). "On the other hand, fructose feeding resulted in an elevation in TNFα as was previously shown in animal models of obesity." (PMID 33138155, 2020). "Inflammation in obesity has long been investigated, and the first evidence in this regard reported upregulated TNF-α expression in adipose tissue and its roles in obesity and its complications." (PMID 31973745, 2020). "In the liver, EPO inhibited gluconeogenesis, attenuated obesity-related inflammatory cytokine expression and production of TNF-α and IL-6, reduced the activation of NFκB and inflammatory signaling, and enhanced insulin-related PI3K signaling." (PMID 33330462, 2020). "It is also known that TNFα levels in VAT increase with obesity, and that TNFα is detrimental to Treg function." (PMID 32773038, 2020). "Obesity is considered an inflammatory disease with elevated levels of some cytokines such as IL-6 and TNF." (PMID 32328497, 2020). "Relationships between higher levels of maternal inflammation markers (e.g., CRP or IL-6 and TNF-alpha inflammatory cytokines) and higher birth weight and obesity in the offspring have also been observed." (PMID 32213887, 2020). "TNF-α, a primary component of the obesity–diabetes mellitus link, is a major pro-inflammatory cytokine involved in the early inflammatory phase and induces NF-κB production." (PMID 32824387, 2020). "It is believed that it is mainly inflammation that is responsible for its increased synthesis in adults with obesity and type 2 diabetes, however, in obese patients, the stimulating effect of TNF-α on its synthesis was also shown." (PMID 33081030, 2020). "Several markers of inflammation, including high-sensitivity C-reactive protein (hsCRP), interleukin (IL)-6, IL-1 and tumor necrosis factor (TNF)-α, have been shown to be associated with obesity, metabolic syndrome, and the risk of chronic diseases." (PMID 32260262, 2020). "We also found increased concentrations of CCL3, IL-1β, and TNFα from among the 38 cytokines, chemokines, and growth factors examined in plasma from ccRCC subjects with obesity versus tumor-free donors with obesity." (PMID 32469992, 2020). "Various studies have shown raised levels of TNF-α in cardio-vascular diseases characterized by presence of low-grade inflammation including obesity, diabetes, metabolic syndrome, and atherosclerosis." (PMID 32424472, 2020).
Obesity (continued). "Considering the close relationships among age, obesity, and immune balances, we preferred to believe the immune intervening method, taking TNF-α inhibitors as the typical example, would provide new insight into the treatment of OSA." (PMID 32787816, 2020). "Our findings suggest that further research should investigate the role of TNF-α as a tool to monitor the effectiveness of diabetes management, particularly in individuals with obesity." (PMID 32089876, 2020). "Resistin is associated with the processes of inflammation because its expression is promoted by pro-inflammatory cytokines such as TNF-α and IL-6 in adipose tissue, and it plays critical roles in the pathogenesis of obesity and insulin resistance." (PMID 33334069, 2020). "For example, the activation of TNF receptor by tumor necrosis factor α (TNFα), a common cytokine elevated during obesity and T2D, activates TAK1, which preferentially activates MKK7, and together with MKK4 will cause the activation of JNK." (PMID 32183037, 2020). "We assessed the levels of the cytokines IL-1β, IL-6, and TNF-α as well as the chemokine RANTES since previous studies have shown that they are elevated in liver of diet-induced rodent models of obesity and contribute to NAFLD pathogenesis." (PMID 32751772, 2020). "The multivariate regression model incorporating cleaning index, approximal plaque index, receptor 1 for tumor necrosis factor-alpha (TNFα-R1) and interleukin-15 (IL-15) had a high power to predict overweight or obesity (AUC = 0.894)." (PMID 32872648, 2020). "Their data showed that microglia activation and consequent TNFα secretion induced mitochondrial stress in POMC neurons that contributed to the development of obesity, suggesting TNFα downregulation to prevent this pathological condition." (PMID 32414136, 2020). "The higher immunoreaction, shown for IL-6 and TNF-α in the older obese rats compared to lean, suggested an inflammatory process at the cardiovascular level due to obesity." (PMID 32188150, 2020). "In mice, genetic manipulations to ablate TNF-α or its receptors ameliorate obesity-induced insulin resistance." (PMID 33072120, 2020). "In obesity/T2D, TNF-α is largely expressed in the adipose tissue by adipocytes, ATMs, monocytes, mast cells, lymphocytes, granulocytes, endothelial cells and fibroblasts." (PMID 32188105, 2020). "As in humans and rodents, also in zebrafish obesity-induced inflammation involves the activation of inflammatory mediators such as chemokines and cytokines (TNFα and interleukins) which are also highly conserved between zebrafish and mammals." (PMID 32635261, 2020). "DIO shifts the activation state of ATMs from M2 anti-inflammatory state to M1 pro-inflammatory state exemplified by an increased expression of genes encoding TNF-α and NOS-2, which contribute to pathophysiological repercussions of obesity." (PMID 33511131, 2020). "Obesity induces a state of moderate chronic inflammation, IL-6 and TNF-α are consistently increased in circulation of obese humans and mouse models." (PMID 32759719, 2020). "Decreased production of NRG4 in obesity is likely due to direct impact of pro-inflammatory cytokines produced in obesity such as TNF-α and IL-1β." (PMID 32175323, 2020). "Metabolic abnormalities within adipose tissue can contribute to obesity complications including excess adipokine secretion: visfatin, leptin, and resistin, but also TNF-α as and plasminogen activator inhibitor-1 (PAI-1)." (PMID 32963689, 2020). "Obesity is associated with chronic low-grade inflammation, and markers of inflammation such as CRP, TNF-α, and IL-6 have been reported to correlate positively with adipocyte size." (PMID 33178661, 2020). "Serum levels of inflammatory markers, such as C-reactive protein (CRP), tumor necrosis factor α (TNF-α), and interleukin 6 (IL-6), correlate with body mass index across the broad range of obesity." (PMID 33266499, 2020).
Obesity (continued). "The catabolic effect of TNF-α on adipose tissue and increased peripheral glucose uptake after neutralizing TNF-α in obese rats indicate its important role in development of insulin resistance and diabetes as a consequence of obesity." (PMID 32089876, 2020). "These macrophages and other immune cells infiltrated in the adipose tissue are a source of TNF-α, IL-6, and other cytokines that links obesity with inflammation and IR." (PMID 33511131, 2020). "A recent study suggest that TNF can contribute to insulin resistance as diet‐induced obesity triggers TNF‐dependent augmentation of circulating inflammatory monocytes independent of adiposity markers or expansion of adipose tissue." (PMID 33038072, 2020). "As the majority indicated that women with obesity, BMI ≥ 34.5 kg/m2, showed significant increase in TNF-α level." (PMID 32893859, 2020). "We found that most of the analyzed cytokines (IL-1β, IL-8, IL-10, TNF-α, tPAI-1, MCP-1, and adiponectin) were associated with obesity." (PMID 32545403, 2020). "In addition to TNF-α, other humoral agents associated with obesity might also be contributing to the activation of WNT signaling like IL-1β and adiponectin, which is decreased in the obese state and is not an inflammatory cytokine that can modulate GSK3β/β-Catenin signaling pathway." (PMID 32811441, 2020). "Hypertrophic adipocytes undergo necrotic-like death in obesity, and increased expression and secretion of pro-inflammatory cytokines, including TNF-α, IL-6, IL-8, and MCP-1." (PMID 32452515, 2020). "In the present study, the obesity condition increased serum TNF-α and IL-1β, and the exercise protocol was sufficient to revert this parameter." (PMID 32847099, 2020). "TNF-α in obesity has been considered mainly pro-inflammatory as it activates immune cells, particularly monocytes and macrophages into a pro-inflammatory phenotype, M1 versus M217." (PMID 33033337, 2020). "PRAT in pigs with obesity-related metabolic dysfunction showed elevated levels of pro-inflammatory macrophage infiltration and TNF-α expression." (PMID 33282920, 2020). "High TNFα levels are observed in the WAT during obesity, and they have profound effects on adipocyte metabolism by impairing triglyceride synthesis and storage and inhibiting adipocyte differentiation." (PMID 32481686, 2020). "The first report establishing a link between inflammation and obesity revealed augmented levels of tumor necrosis factor α (TNFα) in AT of obese mice compared with lean controls." (PMID 32012784, 2020). "In vivo study with fucoxanthin and its metabolite’s actions against the characteristics associated with obesity, demonstrated reduction of serum and hepatic levels of triglycerides and inflammatory cytokines like PGE2, nitric oxide, IL-1, and TNF-α." (PMID 32903449, 2020). "TNF is upregulated in the presence of obesity and impacts the expression of other multiple inflammatory factors such as IL-6 and LCN2 that promote, exacerbate, and sustain chronic systemic inflammation and insulin impairment." (PMID 31892368, 2019). "The expanded mass of dysfunctional adipose tissue in obesity is reportedly a source of several proinflammatory molecules, such as TNF-α, IL-6 and MCP-1, which are predominantly produced by the stromal-vascular cells (SVCs) within adipose tissue." (PMID 30813240, 2019). "Pro-inflammatory adipokines such as leptin, Tumor Necrosis Factor-alpha (TNF-α), interleukin (IL)-6, IL-1, IL-8, and resistin are increased in obesity and are associated with insulin resistance, type 2 diabetes and cardiovascular disorders." (PMID 31475003, 2019). "Inflammation in obesity is manifested by increased circulating levels of classical pro-inflammatory cytokines, such as TNF and altered levels of adipokines, including leptin, resistin, and adiponectin." (PMID 31024226, 2019).